FHL2 (four and a half LIM domains 2)
Diseases named in the same sentence as FHL2 in open-access papers (continued):
Sharing a sentence is not in itself a finding about the gene and the disease.
tumor (continued). "On the contrary, tumours derived from the downregulation of FHL2 in FOXK1-overexpressed cells were markedly smaller than those of the FOXK1-treated mice from 15 to 30 days." (PMID 27892920, 2016). "Consistent with mRNA results, AKT1 protein levels in the tumor tissues derived from FHL2-overexpressing COV434 cells were significantly higher than that in tumor tissues derived from control COV434 cells." (PMID 27415427, 2016). "Compared with the FOXK1-overexpressing cells, the FHL2 downregulation observed in FOXK1-overexpressing cells led to a significant reduction of visible tumours in the liver and lung, which correlated to a lower number of metastasis loci." (PMID 27892920, 2016). "AKT1 mRNA levels in the tumor tissues derived from FHL2-overexpressing COV434 cells were significantly higher than that in tumor tissues derived from control COV434 cells." (PMID 27415427, 2016). "Third, our data showed that KLF8 had a critical role in FHL2-mediated tumor growth, EMT and metastatic phenotypes in vitro and in vivo." (PMID 26320172, 2015). "MALL, FHL2, PHLDA, NR4A3 and CTGF are known oncogenic factors and its gene expression is negatively associated with tumor-free survival and/or proliferation." (PMID 26187749, 2015). "The KLF8 stable-transfectant group showed significantly increased proliferation rates and tumor vessel density than those in the vector group, whereas knockdown of FHL2 inhibited the growth rate and tumor vessel density in the KLF8-overexpressing group." (PMID 26320172, 2015). "FHL2 expression tended to be higher in metastatic tumor cells compared to primary tumor cells (P<0.06)." (PMID 23383046, 2013). "Taken together, these data show that silencing FHL2 reduces murine tumor cell invasion and migration in vitro." (PMID 23383046, 2013). "Using xenograft experiments, we showed that FHL2 silencing markedly reduced tumor growth and lung metastasis occurence in mice." (PMID 23383046, 2013). "Previous studies showed an interaction between FHL2 and β-catenin resulting in enhanced β-catenin-dependent transcriptional activation in different tumor cell lines as HEK293, SW480, and A375." (PMID 23341242, 2013). "Quantification of the tumor samples confirmed that FHL2 silencing reduced tumor volume by about 2-fold compared to control tumors, which is consistent with the anticancer activity of FHL2 silencing that we found in vitro." (PMID 23383046, 2013). "The level of FHL2 transcript was significantly increased in tumor samples, compared to normal adjacent intestinal tissues." (PMID 20442768, 2010). "To test the effect of FHL2 deficiency on tumor growth, we measured the sizes of polyps in ApcΔ14/+FHL2+/+ and ApcΔ14/+FHL2−/− mice and carried out Wilcoxon Rank Sum test to determine if there was a difference in tumor size between the two genotypes." (PMID 20442768, 2010). "Based on this, we hypothesized that FHL2 overexpression might affect tumor cell sensitivity to afatinib." (PMID 40482916, 2025). "Furthermore, the effect of afatinib treatment was evaluated in tumor xenograft models established with H1703 cells with FHL2 overexpression." (PMID 40482916, 2025). "EpICD associates with β-catenin and cofactor FHL2 (four and a half LIM domain protein 2) to form a transcriptome complex that translocates into the nucleus to modulate the transcriptional activity of target genes, such as c-Myc and promote tumor progression." (PMID 39996844, 2025). "FHL2 overexpression significantly enhanced tumor growth rates in both vehicle-treated and afatinib-treated nude mice xenografts, suggesting that FHL2 promotes resistance to afatinib and facilitates tumor progression." (PMID 40482916, 2025). "Furthermore, western blot analysis summarized that the expression level of FHL2 was decreased in tumor tissues from the sh-DLX6-AS1 group compared with the sh-NC group." (PMID 32774164, 2020). "Researches on FHL2 has focused on examining its role in tumor cells growth and metastasis." (PMID 33092075, 2020).
tumor (continued). "Functional analysis revealed that DLX6-AS1 might serve as a tumor promoter in the development of OC by upregulating FHL2 expression via competitively binding to miR-195-5p in vitro and in vivo." (PMID 32774164, 2020). "Besides, FHL2 overexpression destroyed the inhibitory development of OC cells triggered by miR-195-5p enrichment, suggesting the tumor promoter role of FHL2 in OC." (PMID 32774164, 2020). "Quantification of the FHL2 immunosignal indicated that the immunosignal positivity, defined as the percentage of FHL2-positive cells relative to the total cells, was significantly increased in the tumor tissues compared with the control tissue (Ctrl) (p < 0.001)." (PMID 33092075, 2020). "Furthermore, the immunosignal intensity of FHL2 in tumor tissue was significantly higher compared with that of control tissue (p < 0.01)." (PMID 33092075, 2020). "Since FAK46 and FHL228,47–49 are upregulated in several types of cancers, further studies are needed to test whether FHL2 mediate tumor cell invasion in these malignancy." (PMID 31040292, 2019). "We found that FHL2 was overexpressed in human GCT tumor tissues." (PMID 27415427, 2016). "The FOXK1 stable transfectants group showed a significant increase in the proliferation rate and tumour vessels compared with those observed in the vector group, whereas the knockdown of FHL2 inhibited the growth rate and tumour vessels in the FOXK1-overexpressed group." (PMID 27892920, 2016). "FHL2-induced increase in AKT1 may also be involved in mediating TGF-α/ERBBs autocrine/paracrine loops in GCT tumor cells." (PMID 27415427, 2016). "To examine whether FHL2 plays a role in GCT tumor cell growth, we used FHL2 siRNA to knock down FHL2 in KGN cells." (PMID 27415427, 2016). "In the present study, FHL2 silencing may have inhibited cell proliferation independently of cell death since FHL2 was found to regulate tumor cell growth through the control of G1/S transition during cell cycle rather than apoptosis." (PMID 23383046, 2013). "We found that FHL2 silencing strikingly reduced tumor size compared to control cells." (PMID 23383046, 2013). "The results showed that tumor sizes in ApcΔ14/+FHL2−/− mice were not significantly different from those in ApcΔ14/+FHL2+/+ mice (p>0.2, Wilcoxon Rank Sum test), suggesting that loss of FHL2 activity does not affect tumor growth." (PMID 20442768, 2010). "In this study, tyrosine‐phosphorylated FHL2 in the cells was involved in the delayed release from G2/M arrest induced by irradiation, prolonging the time for cells to repair damaged DNA and decreasing the sensitivity to irradiation treatment in tumor cells, such as MCF‐7." (PMID 33932144, 2021). "In addition, FHL2 can also promote tumor growth by upregulating Ras signaling." (PMID 31935687, 2020). "However, the molecular mechanism by which KLF8 affects FHL2-mediated tumor proliferation, EMT and metastasis remains unknown." (PMID 26320172, 2015). "And, previous studies have shown the tumor-growth-inhibition effects of FHL1 and FHL2 was mediated by TGFβ/smad signaling." (PMID 31935687, 2020). "FHL2 expression was determined by immunohistochemistry in age-matched normal human ovarian tissues and GCT tumor tissues." (PMID 27415427, 2016). "Increased AKT1 (induced by overexpression of FHL2) would in turn promotes the activation of NFκB and AP-1, forming a positive-feedback loop to drive GCT tumor malignant progression." (PMID 27415427, 2016). "In multivariate analysis, tumour differentiation, AJCC stage, FOXK1 expression and FHL2 expression each had significant prognostic value for overall survival." (PMID 27892920, 2016).
tumor (continued). "Silencing of FHL2, a β-catenin interacting protein, reduced WNT signaling in OS cells, the expression of WNT5A and WNT10B and tumor formation and lung metastasis in a mouse OS model." (PMID 25992885, 2015). "The transcriptional co-factor FHL2 (four and a half LIM domains protein 2) acts as an oncoprotein or as a tumor suppressor depending on the tissue context." (PMID 23383046, 2013). "In this murine model, introduction of a biallelic deletion of FHL2 into mutant ApcΔ14/+ mice substantially reduces the number of intestinal adenomas but not tumor growth, suggesting a role of FHL2 in the initial steps of tumorigenesis." (PMID 20442768, 2010). "When injected s.c. into BALB/c nude mice, Ras- and p53DD-cotransduced FHL2-null fibroblasts induced tumor formation in 4/4 mice, whereas no tumor developped in 4 mice injected with FHL2−/− cells transduced with p53DD alone." (PMID 19018287, 2008). "Quantification of the FHL2 immunosignal indicated that both the immunosignal positivity (percentage of the FHL2-positive cells relative to the total cells) and immunosignal intensity in the GCT tumor tissues were significantly higher than in the control tissues (P<0.001)." (PMID 27415427, 2016). "However, the molecular mechanism by which FOXK1 synergizes with FHL2 tumour proliferation, EMT and metastasis is not well defined." (PMID 27892920, 2016). "Among these 87 patients, FOXK1 or FHL2 expression in tumour samples was found to be significantly correlated with tumour differentiation, lymph node metastasis, TNM stage, serosal invasion and tumour size; however, it was not correlated with gender, age or location." (PMID 27892920, 2016).
cardiovascular diseases (6 papers, 2019 to 2025). "While FHL2 is well-studied in oncology, cardiovascular diseases, inflammation, and cell differentiation, its role in metabolism has only recently gained attention." (PMID 40064804, 2025). "Given the pleiotropic nature of FHL2 and its involvement in numerous cellular pathways, the effect of FHL2 depletion on cardiovascular diseases must be assessed through in vivo studies." (PMID 38664060, 2024). "Increasing evidence demonstrated that FHL2 and its protein product has a function in cardiovascular disease." (PMID 32682418, 2020). "In summary, the protein–protein interaction data and our in vivo reporter system has led us to identify FHL2 as a promising candidate for regulating RUNX2 activity in vascular smooth muscles and potential therapeutic target for cardiovascular diseases." (PMID 38664060, 2024).
infection (6 papers, 2017 to 2023). The state of being infected such as from the introduction of a foreign agent such as serum, vaccine, antigenic substance or organism. "In this study, we observed an association between the protein level of FHL2 and the infection of Caco2 cells with SARS-CoV-2." (PMID 38203523, 2023). "The different phenotypes observed in vivo among the various organs suggest that ElrA and FHL2 have differential roles depending on the conditions encountered by E. faecalis during infection." (PMID 29379180, 2018). "To further characterize the specific role of NK cells in the defect of IFNγ level in infected FHL2−/− mice, we next analyzed the intracellular production of IFNγ in WT and FHL2−/− lung NK cells following infection." (PMID 28243234, 2017). "The fold increase of IFNγ transcripts in the lungs after 24 h of infection was also significantly higher in WT mice compared to FHL2−/− mice." (PMID 28243234, 2017). "In summary, cellular infection by SARS-CoV-2 induces an elevation in the expression level of FHL2." (PMID 38203523, 2023). "We transferred purified FHL2−/− or WT NK cells into FHL2−/− mice at the time of infection." (PMID 28243234, 2017). "Interestingly, the neutrophil recruitment and activation defect was compensated by the transfer of purified WT NK cells into FHL2−/− mice at the time of infection." (PMID 28243234, 2017). "This suggests that FHL‐2 may be produced in planta during the infection or colonisation event." (PMID 31420965, 2019). "In accordance with the previous results obtained in FHL2−/− mice, upon infection with 5 × 105 cfu S. pneumoniae, 88% (7 out of 8) of the FHL2−/− mice that received FHL2−/− NK cells (FHL2−/− NK cells → FHL2−/− mice) died." (PMID 28243234, 2017).
bacterial infection (2 papers, 2017 to 2018). "Interestingly, in NK cells purified from the peripheral blood of patients with bacterial infection, FHL2 was mainly located in the nucleus." (PMID 28243234, 2017).
cardiac disease (2 papers, 2014 to 2017). "Altogether, these data suggest that FHL2 expression is negatively associated with HCM and more generally with cardiac disease." (PMID 25358972, 2014).
metabolic disease (2 papers, 2023). A congenital disorder (due to inherited enzyme abnormality) or acquired (due to failure of a metabolically important organ) disorder resulting from an abnormal metabolic process. "Four and a half LIM domains 2 (FHL2) is a scaffolding protein, whose involvement in metabolic disease has recently been demonstrated." (PMID 36901761, 2023).
kidney diseases (1 paper, 2019). "An advantage of FHL2 inhibition is that systemic FHL2 gene knockout mice doesn’t develop side effects after long-term follow up, suggesting FHL2 inhibition is a safe and effective intervention to treat kidney diseases." (PMID 31040292, 2019). "In-vivo and in-vitro experiments showed FHL2 inhibition prevent podocyte Rac1 activation without altering normal biological function, pointing out FHL2 inhibition is a good alternative of systemic Rac1 inhibition in treating kidney diseases." (PMID 31040292, 2019).
neurodegenerative disease (1 paper, 2025). A disorder of the central nervous system characterized by gradual and progressive loss of neural tissue and neurologic function. "cg09809672 lies within the FHL2 gene, which is implicated in cell senescence and age-related pathologies, including cardiovascular and neurodegenerative diseases." (PMID 41351063, 2025).
FHL2 also shares sentences with these, for which no sentence is quoted: hypertrophy (2 papers); Hypofibrinogenemia (2); idiopathic pulmonary fibrosis (2); Myocardial fibrosis (2); myopathies (2); non-small cell lung carcinoma (2); acute tubular necrosis (1); alveolar rhabdomyosarcoma (1); autoimmune lymphoproliferative syndrome (1); breast neoplasm (1); channelopathy (1); chronic granulomatous disease (1); colon adenocarcinoma (1); depression (1); endocervical adenocarcinoma (1); esophageal carcinoma (1); esophageal squamous cell carcinoma (1); familial dilated cardiomyopathy (1); familial isolated dilated cardiomyopathy (1); fibrosarcoma (1); gastric cancer (1); Glucose intolerance (1); head and neck squamous cell carcinoma (1); hypertriglyceridemia (1); hypopharyngeal cancer (1); IgA nephropathy (1); inflammation (1); intestinal polyposis (1); invasive breast carcinoma (1); liver cirrhosis (1).
A further 19 diseases each share a sentence with FHL2 in 1 paper.